OR11H7 (olfactory receptor family 11 subfamily H member 7 (gene/pseudogene))
Description:
Odorant receptor. Activated by isovaleric acid.
Synonyms: formerly OR11H7P
Gene: Protein-coding gene on chromosome 14 (20,229,402 to 20,230,346, forward strand). Ensembl gene ENSG00000258806.
Subcellular location: Cell membrane
Pathways (Reactome):
Sensory Perception: Expression and translocation of olfactory receptors
Homologues: Orthologues: dog OR11H7 (85% identical), pig OR11H7 (84% identical), mouse Or11h7 (80% identical), rabbit OR11H7 (79% identical), mouse Or11h23 (78% identical), rat Or11h23b (78% identical). Paralogues in human: OR11H4 (68% identical), OR11H6 (62% identical), OR11G2 (59% identical), OR11H12 (57% identical), OR11H2 (57% identical), OR11H1 (56% identical), OR11A1 (42% identical), OR9G1 (39% identical), OR10X1 (37% identical), OR9A4 (36% identical), OR9A2 (35% identical), OR9A1P (35% identical), and 21 more.